NOTCH2 (notch receptor 2)
Diseases named in the same sentence as NOTCH2 in open-access papers (continued):
Sharing a sentence is not in itself a finding about the gene and the disease.
congenital heart malformation (1 paper, 2025). A disease that has its basis in the disruption of heart development. "Finally, one variant was identified in two related foetuses in the GREB1L gene, associated with renal agenesis, while in two other related cases, showing congenital heart malformations, a variant was identified in the NOTCH2 gene." (PMID 41153384, 2025).
dementia (1 paper, 2024). Loss of intellectual abilities interfering with an individual's social and occupational functions. "Having observed the differential composition of ARM to be a consistent feature of APOE4 carriers, we examined if the NOTCH2 expression differs between APOE4 carriers and non-carriers in dementia cases." (PMID 38397909, 2024).
dilated cardiomyopathy (1 paper, 2025). Cardiomyopathy which is characterized by dilation and contractile dysfunction of the left and right ventricles. "Patients with hypertrophic cardiomyopathy (HCM) show higher expression of Notch2 and its target gene Hes1 in the left ventricle than patients with dilated cardiomyopathy." (PMID 40104444, 2025).
Down syndrome (1 paper, 2019). "Mutations in Notch2 gene induces Down syndrome and Notch3 mutations lead to cardiovascular disorder CADASIL that causes stroke and vascular dementia with degenerative changes in the vascular smooth muscles." (PMID 31770379, 2019).
dry eye (1 paper, 2015). "A recent report showed that members of the canonical Notch signaling pathway i.e., Notch1, Notch2, Notch3, Jagged1, Dll1, were significantly down-regulated in dry eye as compared to the non-dry eye conjunctival epithelia." (PMID 26818247, 2015).
endothelial dysfunction (1 paper, 2022). In vascular diseases, endothelial dysfunction is a systemic pathological state of the endothelium (the inner lining of blood vessels) and can be broadly defined as an imbalance between vasodilating and vasoconstricting substances produced by (or acting on) the endothelium. "Very recently, we have found that deregulation of Notch2 signalling in osteoblasts plays a central role in MTX chemotherapy-induced bone damage, and Notch2 has been previously shown to play an important role in inflammation-mediated endothelial dysfunction." (PMID 35954226, 2022).
esophageal disease (1 paper, 2025). "Similarly, in a mouse model of esophageal disease, overexpression of activated NOTCH2 impaired goblet cell maturation, increased crypt fission, and accelerated tumor development at the squamocolumnar junction." (PMID 41200204, 2025).
Fanconi anemia (1 paper, 2021). Fanconi anemia (FA) is a hereditary DNA repair disorder characterized by progressive pancytopenia with bone marrow failure, variable congenital malformations and predisposition to develop hematological or solid tumors. "The second most commonly altered genes were FANCC (2/6; 33%) which is a critical component of the Fanconi anemia core complex, and NOTCH2 (2/6; 33%), which is a key part of the Notch signaling pathway that controls the normal morphological development of multicellular organisms." (PMID 34440225, 2021).
Gorlin syndrome (1 paper, 2025). "Genes such as SUFU, which harboured an lpVUS in one of the patients diagnosed at 22 years of age, is known for its association with Gorlin syndrome, while ASXL1 and NOTCH2, identified in another patient, have been implicated in familial CRC." (PMID 40627234, 2025).
head and neck cancer (1 paper, 2020). A primary or metastatic malignant neoplasm affecting the head and neck.
hearing loss (1 paper, 2023). "This genetic dynamic may impair cognitive function of the hearing loss patient and Notch2 may serve as a genetic marker for diagnosis." (PMID 37759187, 2023).
heart failure (1 paper, 2025). Inability of the heart to pump blood at an adequate rate to meet tissue metabolic requirements. "Thus, targeting Notch2-mediated purine nucleotide metabolism may be an attractive therapeutic approach to heart failure treatment." (PMID 40104444, 2025).
hemophagocytic lymphohistiocytosis (1 paper, 2021). "We report the first case with mutations in FLT3, NOTCH2, and KMT2A, and associated hemophagocytic lymphohistiocytosis." (PMID 34292677, 2021).
hepatopathies (1 paper, 2026). "We tested this approach on 9 patients with pediatric hepatopathies with phenotypes ranging from the full clinical ALGS spectrum to isolated neonatal cholestasis and atypical ALGS abnormalities who carried 5 JAG1 and 3 NOTCH2 missense variants of interest." (PMID 41998240, 2026).
heritable pulmonary arterial hypertension (1 paper, 2025). Heritable pulmonary arterial hypertension (HPAH) is a form of pulmonary arterial hypertension (PAH), occurring due to mutations in PAH predisposing genes or in a familial context. "Both pathways induce notch receptor (NOTCH) 2 while inhibiting NOTCH3, thereby promoting the proliferation of PASMCs in heritable pulmonary arterial hypertension (HPAH)." (PMID 40066229, 2025).
hyperuricemia (1 paper, 2017). An abnormally high level of uric acid. "We have now shown that rs60854092 [T/A (F1689I)] of NOTCH2 was significantly associated with hyperuricemia, with the minor A allele being protective against this condition." (PMID 28410202, 2017). "We also identified rs188780113 [G/A (R478C)] of ATG2A as a novel determinant of the serum concentration of uric acid as well as rs115445569 of ACOT11, rs116911833 of TRIM7, and rs60854092 of NOTCH2 as potential novel susceptibility loci for hyperuricemia." (PMID 28410202, 2017). "The remaining four genes (ATG2A, ACOT11, TRIM7, and NOTCH2) may be novel loci that influence the serum concentration of uric acid or confer susceptibility to hyperuricemia." (PMID 28410202, 2017). "Three SNPs (rs115445569 of ACOT11, rs116911833 of TRIM7, rs60854092 of NOTCH2) were related (P < 0.05 in at least one genetic model) to hyperuricemia, although there was no SNP significantly [P < 3.57 × 10−4 (0.05/140)] associated with this condition." (PMID 28410202, 2017). "In addition, rs115445569 [C/T (R64Q)] of ACOT11, rs116911833 [G/A (T80M)] of TRIM7, and rs60854092 [T/A (F1689I) of NOTCH2 were related to hyperuricemia, although the genotypes of these SNPs were not related to the serum concentration of uric acid." (PMID 28410202, 2017).
influenza (1 paper, 2019). An acute viral infection of the respiratory tract, occurring in isolated cases, in epidemics, or in pandemics; it is caused by serologically different strains of viruses (influenzaviruses) designated A, B, and C, has a 3-day incubation period, and usually lasts for 3 to 10 days. "The genes pertaining the skyblue module were enriched in Axon guidance, signaling by NOTCH2, Infectious disease, Influenza Infection, Influenza Life Cycle, Influenza Viral RNA Transcription and Replication, Viral mRNA Translation, and rRNA processing." (PMID 31665046, 2019).
iron deficiency (1 paper, 2013). "Not only did iron therapy reverse lung metastasis, but also reversed iron deficiency-mediated tumor growth, downregulated Snai1, upregulated E-cadherin, and decreased Notch2 expression." (PMID 23800380, 2013).
liver cholestatic diseases (1 paper, 2019). "Genetic tests for liver cholestatic diseases revealed negative results for AGS (JAG1 and NOTCH2)." (PMID 30791938, 2019).
liver inflammation (1 paper, 2022). "Similarly, JAG1-MSC treatment further decreased inflammatory mediators, whereas Notch2 silence abolished the beneficial effect of JAG1-MSCs on APAP-induced liver inflammation." (PMID 35842731, 2022).
lymphopenia (1 paper, 2022). Reduction in the number of lymphocytes. "Mechanistically, Dll1/Notch2-mediated signals were essential for lymphopenia-induced B cell transdifferentiation, for their proliferation, and for their subsequent differentiation into antibody-producing plasma cells." (PMID 35579963, 2022). "Next, we evaluated which Notch ligands drive Notch2-mediated signaling in B cells exposed to lymphopenia." (PMID 35579963, 2022). "Our findings indicate that Notch2-driven B cell transdifferentiation can happen physiologically as a result of Notch ligand/receptor interactions during lymphopenia, and that these interactions represent a critical quantitative input through which mature B cells sense available B cell space." (PMID 35579963, 2022).
macular edema (1 paper, 2026). "Levels of STX3 and NOTCH2, proteins involved in retinal function, were correlated with a diagnosis of macular edema, a record of a visual field exam, and a prescription for latanoprost, highlighting protein-EHR alignment." (PMID 41918763, 2026).
malignant mesothelioma (1 paper, 2021). A malignant neoplasm of the pleura or peritoneum, arising from mesothelial cells. "In a study of the malignant mesothelioma, an invasive tumor of the pleura, pericardium, and peritoneum, Notch2 negatively regulated PI3k-Akt and found that Notch2 could activate PTEN, both of which inhibition of angiogenesis plays a pivotal role." (PMID 36643842, 2021).
medullary thyroid cancer (1 paper, 2022). "Resveratrol increased Notch-2 mRNA, induced apoptosis and suppressed neuroendocrine marker ASCL-1 in medullary thyroid cancer (MTC)." (PMID 35408894, 2022).
metastatic melanoma (1 paper, 2021). A melanoma that has spread from its primary site to another anatomic site. "CYT-high metastatic melanomas had recurrent copy number amplifications in loci 1p12 (NOTCH2), 1q44 (OR2M4), 7q36.1 (KCNH2), 11q13.3 (FGF3/4), 12p11.23 (MED21) and 12q13.3 (R3HDM2) and deletions in 1p22.1 (RHOC, NRAS), 9p21.3 (CDKN2B), 10q23.2 (miR346), 11q23.3 (ATM, CHEK1, ETS1) and 15q15.3 (CASC4)." (PMID 33779796, 2021). "Also, amplifications in loci 1p12 (NOTCH2), 3p13 (MITF), 13q13.3 (FGF3/4, CTTN) and 22q13 (MLK1) were found in both cytolytic subtypes of metastatic melanoma." (PMID 33779796, 2021).
multiple sclerosis (1 paper, 2025). A progressive autoimmune disorder affecting the central nervous system resulting in demyelination. "Recent study has shown that NOTCH2 expression in monocytes predicts interferon β (IFN-β) immunogenicity in patients with multiple sclerosis and hence might be involved in autoimmune or inflammatory diseases." (PMID 41244563, 2025).
myeloid sarcoma (1 paper, 2023). A tumor mass composed of myeloblasts or immature myeloid cells.
myocardial infarction (1 paper, 2023). Gross necrosis of the myocardium, as a result of interruption of the blood supply to the area, as in coronary thrombosis. "miR-15b-5p targets SMAD Family Member 7 (SMAD7), Notch Receptor 2 (NOTCH2), an important player in the regeneration and cardiac repair post myocardial infarction, and Autophagy Related 9A (ATG9A)." (PMID 38132140, 2023).
myopia (1 paper, 2023). "Taken together, we suppose that in high myopia, NOTCH2 signalling inhibition could accelerate secondary lens fibre cell differentiation by activating CDKN1C, the differentiation initiator, and promote accumulation of β/γ crystallin, the specific structural proteins of LFCs, by activating MAF." (PMID 36717696, 2023).
pancreatic adenocarcinoma (1 paper, 2016). "Tarextumab has recently tested in a phase II clinical trial for the treatment of pancreatic adenocarcinoma and pulmonary small cell carcinoma, which exhibit dysregulated NOTCH2 and/or NOTCH3 activity in tumor cells." (PMID 27124156, 2016).
papillary cell renal cell carcinoma (1 paper, 2019). "Low expression of ADAM10 and HES1 are observed in clear cell renal cell carcinoma, while lower expression of HES5 and JAG1 are observed in papillary cell renal cell carcinoma and lower expression of NOTCH2 is observed in chromophobe renal cell carcinoma." (PMID 31690016, 2019). "Taken together with the observation that conditional Notch2 inactivation in the mouse kidney results in renal tubular cysts with microadenomas that could be a precursor to papillary renal cell carcinoma, Notch signaling may play a tumor suppressor role in the kidney." (PMID 31690016, 2019).
papilloma (1 paper, 2010). A benign epithelial neoplasm that projects above the surrounding epithelial surface and consists of villous or arborescent outgrowths of fibrovascular stroma. "In line with the non-redundant roles of Notch1 and Notch2 in keratinocytes is the accelerated papilloma formation in double Notch1/2-deficient mice, suggesting that Notch2 cannot fully compensate for Notch1 loss." (PMID 21042537, 2010).
periodontitis (1 paper, 2024). An acute or chronic inflammatory process that affects the tissues that surround and support the teeth. "Spatial transcriptomics further confirmed that JAG1 expression in basal epithelial cells was markedly increased in the context of periodontitis, with concurrent upregulation of NOTCH2 in macrophages." (PMID 39769019, 2024).
peripheral T-cell lymphomas (1 paper, 2020). "We also found mutations in NOTCH1/NOTCH2 and JAK/STAT genes, previously reported to be mutated in peripheral T-cell lymphomas: NOTCH1 (16/71, 22%), NOTCH2 (14/71, 19%), JAK3 (5/71, 7%), and STAT6 (2/71, 3%)." (PMID 31028364, 2020).
prolactinomas (1 paper, 2017). "Nevertheless, we found that the intracellular active domain of NOTCH2 was significantly increased in the MMQ prolactinoma cell line." (PMID 28915655, 2017). "On the other hand, in prolactinomas harbored by lacDrd2KO female mice, not only Notch1 and Notch3 mRNA levels but also NOTCH2-3 membrane and NOTCH1 active domains were highly expressed in knockout mice compared to their control counterparts, the Drd2loxP/loxP mice." (PMID 28915655, 2017).
pulmonary stenosis (1 paper, 2024). "Jag1 and Notch2 double heterozygous mice exhibit RV hypoplasia, pulmonary stenosis, VSD, and ASD54." (PMID 39085358, 2024).
retinitis pigmentosa (1 paper, 2023). Retinitis pigmentosa (RP) is an inherited retinal dystrophy leading to progressive loss of the photoreceptors and retinal pigment epithelium and resulting in blindness usually after several decades. "A third example is F454 and F2924, two families in which a non-syndromic retinitis pigmentosa phenotype fully segregated with a founder recessive NOTCH2 variant even though this gene is only linked to very distinct autosomal dominant conditions in OMIM." (PMID 37644014, 2023).
scoliosis (1 paper, 2021). A congenital or acquired spinal deformity characterized by lateral curvature of the spine. "This identified 12 CNVs in four scoliosis-associated genes (TBX6, NOTCH2, DSCAM, and SNTG1) as well as eight recessive and 64 novel rare CNVs in 15 additional genes." (PMID 34440387, 2021).
skin melanomas (1 paper, 2021). "Many of them were previously appreciated in the genome of skin melanomas (e.g., MITF, NOTCH2, PD-L1 and JAK2 amplifications, or CDKN2A deletions); however, the CNAs in genomic locations harboring PAX5, ETS1, BCL7, RAD51, APAF1, FOXO3 and CTNNA1 are novel." (PMID 33779796, 2021).
somatotroph adenomas (1 paper, 2020). "A positive correlation has been reported between expression of Notch2/DLL3 pathway and invasion in somatotroph adenomas, and knockdown-Notch2 noticeably inhibited the cell migration in both GH3 cell line and primary tumor cell." (PMID 33425722, 2020).
systemic lupus erythematosus (1 paper, 2025). An autoimmune multi-organ disease typically associated with vasculopathy and autoantibody production. "Effectively, aberrant Notch2 signaling has been observed in clinical samples of patients affected by RA, systemic lupus erythematosus (SLE), and systemic sclerosis." (PMID 41517433, 2025).
T-cell leukemia (1 paper, 2011). A malignant disease of the T-lymphocytes in the bone marrow, thymus, and/or blood. "Later it was found that Notch2 plays a role in CD8 thymocyte maturation and that enforced expression of activated Notch2 invariably resulted in T-cell leukemia in mice." (PMID 22128846, 2011).
T-cell lymphoma (1 paper, 2023). "Moreover, missense mutations were detected in CD44 and CD19 (associated with acute myeloid leukemogenesis), LTK (associated with poorly differentiated adenocarcinoma), NOTCH2 (associated with diffuse large B-cell tumorigenesis), and CNTN2 (associated with T-cell lymphoma)." (PMID 36871023, 2023).
thymic lymphomas (1 paper, 2022). "Some experimental evidence indicates that NOTCH pathways play a role in T-NHL development, for example, NOTCH1 expression is elevated in mouse Υ-radiation-induced thymic lymphomas, whereas NOTCH2 expression is markedly decreased, suggesting that NOTCH2 inactivation is involved in T-NHL." (PMID 35681778, 2022).
tobacco use disorders (1 paper, 2012). "Furthermore, gene AK023526 has been found to constitute a marker for cancer stem cells, and gene NOTCH2 has been associated with tobacco use disorders and certain types of cancer." (PMID 23173873, 2012).
type I diabetes (1 paper, 2020). "In another autoimmune model, the non-obese diabetic (NOD) mouse that develops type I diabetes, heterozygosity for Notch2 does not lead to as significant a reduction in MZ B cells as is typically seen in Notch2+/- mice on a non-autoimmune prone C57BL/6 background." (PMID 33613531, 2020).
Usher syndrome (1 paper, 2012). A syndromic diseae characterized by the association of sensorineural deafness (usually congenital) with retinitis pigmentosa and progressive vision loss. "Several of the top candidate genes include EEF1A1, ROBO1, PLXNA4, SLIT3, NRP1, and NOTCH2, as well as genes associated with the Usher syndrome, PCDH15 and USH2A, and are plausible candidates contributing to the developmental defects in Gbx2−/− mice." (PMID 23144817, 2012).
uterine cancer (1 paper, 2022). Primary or metastatic malignant neoplasm involving the uterine corpus and/or the cervix. "The analysis of the obtained data showed a statistically significant association between the survival rate of uterine cancer patients and the expression of NOTCH2 gene." (PMID 35136410, 2022). "Expression alterations of NOTCH2, NOTCH3, NOTCH4, JAG2, and HES1 were evaluated as independent and significant prognostic factors for uterine cancer patients." (PMID 35136410, 2022). "NOTCH2, NOTCH3, NOTCH4, JAG2, and HES1 may be used as independent and significant prognostic factors for uterine cancer patients." (PMID 35136410, 2022).
vocal cord polyps (1 paper, 2022). "As revealed by QD-IHC, an upregulation of NOTCH2 expression was observed in LSCC tissues compared with vocal cord polyps and a further upregulation was recorded for LSCC tissues from patients with LNM compared to the non-metastatic ones." (PMID 35406495, 2022).